TNF (tumor necrosis factor)
Diseases named in the same sentence as TNF in open-access papers (continued):
Sharing a sentence is not in itself a finding about the gene and the disease.
infection (continued). "However, none of these cell culture experiments were performed in presence of TNF or other cytokines likely to influence outcomes during natural infection of tissues." (PMID 33126536, 2020). "The therapeutic efficacy with micafungin in aspergillosis is strictly induced by the activation of the TLR2/dectin-1 and TLR3/TRIF signaling pathways, which regulate the inflammatory/anti-inflammatory balance during infection, mainly by increasing the production of IL-10 and decreased TNF-α." (PMID 33194839, 2020). "In addition, the TNF and IL-6 protein levels were markedly upregulated in Ppara-/- BMDMs compared with Ppara+/+ BMDMs, at 6 and 18 h after Mabc infection." (PMID 32155958, 2020). "The GO enrichment analysis and KEGG database data showed that the differentially expressed miRNAs and mRNAs were mainly enriched in JNK activity, MAPK phosphatase activity, and the TLR, Jak-STAT and TNF signalling pathways after treatment of FM1 infection with XDY." (PMID 32957919, 2020). "Furthermore, the expression of TNF, IL-6, and IL-1β mRNA and protein levels were significantly increased in Ppara-/- BMDMs, compared with Ppara+/+ BMDMs, after Mabc infection (protein and mRNA, respectively)." (PMID 32155958, 2020). "In addition, it has been recently shown that Ly6Clow monocytes rapidly secrete a large amount of TNF-α during inflammation and infection with L. monocytogenes." (PMID 32101593, 2020). "TNF sets a natural immune response in motion in reaction to an infection." (PMID 33193432, 2020). "However, after infection Sting−/− mice showed increased levels of the inflammatory cytokines IL-17, TNF-α, and IL-6 when compared to the WT animals." (PMID 32404867, 2020). "Besides pathogen infection, proinflammatory cytokines such as tumor necrosis factor α (TNFα) also produces TBK1 activation." (PMID 33193441, 2020). "TNFα concentration was increased during the infection in the co-culture." (PMID 32210941, 2020). "TNF-α contributed to improved macrophage development which stimulates macrophage activation, differentiation and survival of these cells and thus enhances proinflammatory responses in infection." (PMID 33158114, 2020). "A significant (p < 0.05) increase has been noted in TNF-α level at day 3 and 7 post-infection." (PMID 32391391, 2020). "Direct MLKL activation may also avoid the potential accumulation of RIPK3-driven oxidative stress upon stimulation of the necrosome as has been reported following TNFα/Smac mimetic treatment, pathogen infection or necrosome formation." (PMID 32826875, 2020). "Conversely, we observed that infection of murine macrophages showed a significant increased secretion of only two pro-inflammatory cytokines (IL-12p70, and TNF) and one anti-inflammatory cytokine (IL-10) in infected RAW264.7 cells, with similarly low levels of these cytokines in mock-infected cells." (PMID 32163514, 2020). "After 24 h of infection, the TNF-α levels increased to 10.71–11.75 pg/mL." (PMID 32221396, 2020). "Such TNF-α and IL-1β overexpression lasted for at least 8 h post-infection." (PMID 32117805, 2020). "As expected, following M. tuberculosis infection, TNF-/- mice succumbed to the infection just 3 weeks post-infection, and dramatically lost bodyweight, which was accompanied by severe clinical neurological signs and brain shrinking when compared with TNFf/f mice." (PMID 32742607, 2020). "Patients who developed an infection yielded significantly lower TNF-α values (86 vs 192 pg/mL, p = 0.030) and a trend towards higher IL-10 values (122 vs 84 pg/mL, p = 0.071) following ex vivo whole blood stimulations when compared to patients not developing an infection." (PMID 33237337, 2020). "Mice with complete loss of function of TNF failed to keep intact the recruitment of plasmablast-producing IgA+, IgG+, and IgM+ at week 3 post-infection, leading to a significant decrease of these cells when compared with TNFf/f and BTNF-/- mice." (PMID 32742607, 2020).
infection (continued). "The gene expression of iNOS was also significantly increased following H9N2 AIV infection (P < 0.01), while that of TNF-α, IFN-γ and iNOS was significantly downregulated in the H9N2 AIV infection group with AL feeding, as compared with the infection group (P < 0.01 and P < 0.05)." (PMID 33193136, 2020). "For teleosts, which rely on non-specific immune processes to enhance their immune response and resist pathogen infection, cytokines such as TNF-α, IL-1β, IL-6, IL-10, IL-12, and TGF-β, primarily produced by activated macrophages, also play an important role in the immune system." (PMID 32457762, 2020). "The corticosteroids/anti-TNF-α combination can indeed synergize in lowering TNF-α levels through different and independent mechanisms, with the consequent increase of the anti-inflammatory effect, but at the expense of a rise in the risk of infection." (PMID 32397174, 2020). "Moreover, we explored the influence of ZAPL and ZAPS on the expression of IFN-β, MxA, TNF, and IL-6 at 12 h after infection." (PMID 32922375, 2020). "However, at day 50 and 99 post infection, these cytokine subsets were reduced resulting in cytokine subsets dominated by expression of TNFα." (PMID 31993218, 2020). "In addition, for both UC and CD patients, safety profiles were improved with vedolizumab vs anti-TNFα (numerically lower rates of serious infections; significantly lower rates of SAEs)." (PMID 32640990, 2020). "Interestingly, treating macaques with TNF neutralizing agents resulted in drastically increased extrapulmonary dissemination and the development of disseminated disease within 8 weeks post-infection." (PMID 32161724, 2020). "There was low level expression of TNF-α throughout the infection and there was a surge at 20 dpi." (PMID 32076422, 2020). "TLRs mediate several processes in the inflammatory cascade upon LPS stimulation, such as the production of TNFα and other inflammatory cytokines, chemokines, and adhesion molecules through activation of NFκB, which leads the immune system to detect infection and react to it." (PMID 31947975, 2020). "However, there was a significant decrease in the secretion of IL-12 and TNF-α upon infection of RAW-ΔTLR4 cells with Ms_Rv1954A compared to Ms_Vc." (PMID 33163415, 2020). "In our model, M. haemolytica tended to affect the cell viability of PBECs in the LLI system, which may result in lower TEER values and higher IL-6 and TNF-α release after infection." (PMID 32747652, 2020). "An efficiently developed or preexisting T helper 1 (Th1) response and the secretion of cytokines that activate phagocytic activity on macrophages and stimulate T cells, interferon (IFN)-γ, IL-12, and TNF-α are often observed to contain the infection during the subclinical period." (PMID 33312173, 2020). "Upon antigen encounter TRM cells rapidly produce different effector molecules including cytotoxic factors like granzyme B (GzmB) or perforin, and inflammatory cytokines such as Interferon-γ (IFN-γ) and Tumor Necrosis Factor (TNF) as observed in different organs and upon various infection model." (PMID 33202970, 2020). "For the intravenous infection, mice infected with strain P15 had significantly higher production in the brain of the Th2 cytokines IL-4 and IL-10, as well as the inflammatory cytokine TNF-α." (PMID 33103620, 2020). "The 3A and 2B proteins of PV may clear the TNF receptor from the cell membrane after 4 h of infection by affecting the host cell endoplasmic reticulum-glial protein transport pathway, thus inhibiting TNF-mediated apoptosis early in infection." (PMID 32582091, 2020). "Remarkably, CSF2 (encoding granulocyte-macrophage colony-stimulating factor), IL-6 (interleukin-6), IL-12B (interleukin-12 subunit beta), CSF3 (granulocyte colony-stimulating factor), and TNF (tumor necrosis factor) were extremely highly expressed upon infection with WT V. vulnificus (log2 FC > 8)." (PMID 32817457, 2020).
infection (continued). "In mice, vaccine-induced TRM cells patrol the liver sinusoids, form aggregates around infected hepatocytes and, based on expression of molecules such as GzmB, IFN-γ and TNF-α, potentially exert infection control through direct lysis and/or cytokine-mediated mechanisms." (PMID 33202970, 2020). "Elevated levels of IFNγ and TNF were found in Ifnar1−/− mice on day 14 p.i. compared with WT controls, but the levels subsequently declined over the course of infection, and TNF levels were significantly lower in Ifnar1−/− mice on days 28 and 56 p.i. compared with WT controls." (PMID 32101732, 2020). "During the chronic stage of infection (8 weeks), cytokine levels in Cbs+/− and WT mice were similar except for a lower TNF-α and IL-10 levels in Cbs+/− mice, which might be due to reduced percentages of neutrophils and lymphoid cells mostly in the spleen." (PMID 31992699, 2020). "In concert with the pyretic response, TNF-α and IL-6 were elevated in response to infection." (PMID 33306742, 2020). "Thus, after infection, TNFα and TNFR1 proteins were mainly displayed in the cytoplasm of inflammatory cells." (PMID 32685099, 2020). "Functional analysis of these DEGs demonstrated that the TNF signaling pathway, the toll-like receptor signaling pathway, complement and coagulation cascades, and cytokine–cytokine receptor interaction were both enriched in PmQ and PmCQ2 infection." (PMID 32851030, 2020). "Finally, to determine if IL-8 production is affected during the period of infection where p38 phosphorylation is dampened, we shortened the TNFα stimulation to 4 h." (PMID 32373107, 2020). "TNFα is involved in the process of infection and immune responses." (PMID 32121588, 2020). "We further studied the degranulation of these cells after contact/infection with ZIKV by measuring β-hexosaminidase release as well as the expression profiles of TNF-α (tumor necrosis factor-α), IL-6 (interleukin-6), IL-10 (interleukin-10) and VEGF (vascular endothelial growth factor)." (PMID 32316163, 2020). "Additionally, the level of TNF-α mRNA in the lungs at 3 days post-infection was significantly lower in klotho KO mice than in klotho WT mice." (PMID 33329595, 2020). "Interestingly, macrophages transfected with let-7f and let-7g antagomirs also released more TNF-α upon infection, further sustaining the connection between increased SUMOylation and inflammation in macrophages." (PMID 32994335, 2020). "In contrast with control animals, mice with pulmonary TB showed a significant decrease in NE, DA, EP and 5-HT in the hypothalamus and cerebellum from day one of infection, when in this model there is a high production of pro-inflammatory cytokines in the lungs, such as TNF-α and IL-1-β." (PMID 33322180, 2020). "In contrast, the production of Rv0297 in the later stages of infection and the subsequent induction of TNF-α release may aid in granuloma maintenance." (PMID 33042856, 2020). "IL-12, IFN-γ and TNF-α all showed significant downregulation after infection." (PMID 32085719, 2020). "However, infection of AAV6-shRNA-AK149641 resulted in significantly lower expression levels of TNF-α and IL-6." (PMID 32929606, 2020). "Furthermore, in human CL, CD4+ Th1 immune response with the production of IFN-γ, TNF-α, and IL-12, as depicted in, has been correlated with infection control via macrophage activation and parasite destruction." (PMID 32656269, 2020). "Although B. infantis BL2416 attached to host cells in lower rate than L. casei ATTC334 and B. breve JCM1192 strains, it promoted IFN-γ and TNF-α production which may contribute to the clearance of infection." (PMID 32545606, 2020). "Various inflammatory cytokines (IL-1β, IL-6, IL-12, TNF-α) are increased inleptospirosis as an immune response to the infection, however, this increase may behigher in severe stages of the disease." (PMID 32578717, 2020).
infection (continued). "Therefore, vICA-mediated inhibition of CASP8 is crucial during the early stages of infection where TNF signaling represents the most prominent inflammatory pathway leading to CASP8 activation." (PMID 33126536, 2020). "TNF-α is required for the establishment of memory and control of infection." (PMID 32185141, 2020). "Since IL-6 and TNF-α are commonly induced immediately after infection, we measured cytokines in plasma at earlier time points (2 and 6 h) after stimulation with S. suis than determined in the in vivo-infection experiment." (PMID 31947746, 2020). "Furthermore, we discuss the role of TNF in the generation of proinflammatory macrophages in mouse models of infection and summarize briefly the potential consequences of anti-TNF treatment for infectious diseases." (PMID 32760383, 2020). "In contrast, in additional analysis, we showed that infection with UT127 could induce the expression of genes such as TNF, IL1B, and PTGS2, which together induce activation of apoptosis in MoCT but not in MoTB." (PMID 32391286, 2020). "Also, the infection witnessed an upsurge in pro-inflammatory cytokines and chemokines (IL-6, IL-1β, TNF-α, IFN-γ, and IL-8)." (PMID 33262955, 2020). "The level of TNF-α mRNA in the lungs of klotho WT mice gradually increased after infection, whereas those of klotho KO mice significantly increased at 1 day post-infection and subsequently decreased at 3 days post-infection." (PMID 33329595, 2020). "We found that 11g-treated C. albicans could increase the secretion of TNF-α, IL-10, IL-12/23 p40, and IL-6 in macrophages after 6 h post-infection." (PMID 32695076, 2020). "Production of TNF-α is often associated with macrophage activity, among other outcomes; however, only a small percentage of splenic macrophages stained positively for TNF-α (1–2%) and showed consistent changes over the course of infection across all treatments." (PMID 32673362, 2020). "However, impaired expression of CD-associated genes ATG16L1 or IRGM in THP-1 macrophages and NOD2 in NOD2−/− murine peritoneal macrophages led to an increased AIEC intracellular replication and to the secretion of IL-6 and TNF-α upon AIEC LF82 infection." (PMID 32466328, 2020). "Endogenous production of G-CSF is largely triggered by infection and tissue damage in response to production of several pro-inflammatory stimuli such as the cytokines interleukin-1 beta (IL-1β) and tumor necrosis factor-alpha (TNFα), as well as bacterial lipopolysaccharides (LPS)." (PMID 33233675, 2020). "In this article we want to examine the possible correlation between therapy with TNF inhibitors and the increased risk of SARS-CoV-2 infection, and the possible paradoxical therapeutic efficacy in patients with ongoing infection, especially in phase two and three." (PMID 34513612, 2020). "If CD8+ cytotoxicity and the production of pro-inflammatory cytokines (INF-γ TNF-α) are critical for the efficiency of infection resolution in mice, they may also contribute to immunopathology and lung injury." (PMID 32066441, 2020). "Since the transcriptional and translational expression of TNF-α increased during Ms_YrbE3A and BCG_YrbE3A infection, we conducted experiments to understand whether YrbE3A can also affect the survival rate of mycobacteria." (PMID 32316659, 2020). "In addition, proinflammatory cytokines such as TNF-α, IL-1β, IL-6, and IL-8 trigger and rapidly amplify the inflammatory response to limit the spreading of the infection." (PMID 32373312, 2020). "The possible explanation of the synergistic elevation of both TNF-α and IL-8 levels is that the endometrial cells respond to infection by activation of TLRs and thereafter stimulate the release of pro-inflammatory cytokines as TNF-α, chemokines as IL-8 and prostaglandins." (PMID 32368278, 2020).
infection (continued). "Furthermore, another study showed that steroid hormones increased interleukin (IL)-10, tumor necrosis factor (TNF)-α, IL-6, and IL-8 cytokines in decidual stromal cells to defend against infection by B. streptococcus." (PMID 31859912, 2020). "Another retrospective cohort study, done by four centers in the USA (Cleveland Clinic, Johns Hopkins Hospital, University of Miami, and Brigham and Women’s Hospital) aimed to identify the incidence of serious infections in HIV-patients treated with TNF-α inhibitors after being diagnosed with HIV." (PMID 33209528, 2020). "In the last phase of the infection from 14-21dpi, all treatments showed increases in the percentage of TNF-α+ cells, with the greatest increase observed in 5th cutting chloroform extracts (75%) to levels 47.4 and 36.2% above both the control and 1st cutting chloroform extract diets (P < 0.0001)." (PMID 32673362, 2020). "It has also been suggested that TNF-α is involved in the enhanced activity of matrix metalloproteinases (MMPs) in the thymus during infection by Plasmodium berghei in mice, which have been related to thymus dysfunction via the alteration of extracellular matrix (ECM) proteins." (PMID 32823553, 2020). "As inflammation could reflect the infection level and the early stage of the healing process, the expression of two typical proinflammatory factors (IL-6 and TNF-α) was analyzed by immunohistochemistry at the end of the experiment." (PMID 32575392, 2020). "In reference to the immunomodulatory role of LL-37, P. bovis upregulated mRNA expression of TNF-α, Cxcl-1, and IL-1β in murine phagocytic J774.A1 cells (at 2 and 8 h post-infection), whereas co-stimulation with LL-37 decreased concentrations of TNF-α, Cxcl-1, and IL-1β mRNA expression (p < 0.05)." (PMID 32117805, 2020). "TNF-dependent signaling is intricately associated with CMV disease and infection." (PMID 33126536, 2020). "Additionally, enhanced production of IL-17, IL-6, and TNF-α were detected in BAL from Sting-/- mice after infection." (PMID 32404867, 2020). "Moreover, our KEGG pathway analysis of highly upregulated DEGs indicated that the TNF and NF-κB signaling pathways were enriched in HeV-infected HeLa and PaKi cells, suggesting that HeV-infection induced certain innate antiviral responses in both cell lines." (PMID 32508793, 2020). "As we previously reported, mice with complete loss of TNF gene showed increased mycobacterial burden in the brain, lung, and spleen when compared with TNFf/f mice; also at week 3 post-infection, a striking increased bacterial burden was found in TNF-/- mice compared with the B-TNF-/- mice." (PMID 32742607, 2020). "Cytokines include chemokines, interferons, interleukins (IL), lymphokines, and tumor necrosis factors (TNF) are produced by many types of cells that include macrophages and lymphocytes that are essential in host immune responses to infection, inflammation, trauma, sepsis, cancer, and reproduction." (PMID 33363329, 2020). "IL-8 and TNF-α are well-established inflammatory readouts upon infection." (PMID 32994335, 2020). "However, 5 days after infection (day 5), the levels of IL-6, TNF-α, and IL-1β in group ZE were significantly lower than the model group." (PMID 32486242, 2020). "Interestingly, the secretion of TNF-α has the ability to recruit neutrophils to the site of infection as well." (PMID 32545470, 2020). "The cytokine TNF is a central player in inflammatory diseases and infections." (PMID 32914580, 2020). "Therefore, the data obtained here in cultures stimulated with TNFα, revealed another pathway to explain the protective role of tiger nut against S. enteritidis, independently of its capacity to avoid infection by agglutinating the bacterium." (PMID 33379352, 2020). "Prevention of TNF alpha production in patients at risk may prevent hospital admission and deterioration of infected patients at risk of ARDS from this infection." (PMID 32922301, 2020).